SIRT1 (sirtuin 1)
Diseases named in the same sentence as SIRT1 in open-access papers (continued):
Sharing a sentence is not in itself a finding about the gene and the disease.
cancer (continued). "The inactivation of HIC-1 resulted in upregulated SIRT1 expression in normal or cancer cells." (PMID 24489730, 2014). "SIRT1 is also responsible for site-specific deacetylation at H3K18Ac in cancer cells." (PMID 25486244, 2014). "Given our findings that JQ-101 can selectively suppress cancer cell growth by inducing tumor cell apoptosis and senescence, and significantly inhibit cancer cell invasion, these results suggest a potential role of JQ-101 or a derivative in a SIRT1-targeted approach to cancer therapy." (PMID 25189993, 2014). "This suggests that JQ-101 suppresses cancer cell growth by targeting SIRT1." (PMID 25189993, 2014). "Moreover, there is growing evidence strongly suggesting that SIRT1 has a role in cancer progression." (PMID 25189993, 2014). "Interestingly, silencing SIRT1 eliminated autophagy stimulation by resveratrol and by nutrient deprivation in human cancer cell lines." (PMID 25247581, 2014). "It is currently unknown whether SIRT1 regulates the metabolic effects of MYC in cancer; however, based on these findings, it is likely that SIRT1 can induce expression of MYC target genes important in mediating metabolic reprogramming." (PMID 25085992, 2014). "In PCa, sirtuin 1 has been involved in autophagy, and SIRT1 knockdown induced PIN development, suggesting that SIRT1 might be a tumor suppressor gene in this cancer model." (PMID 24127549, 2013). "Nevertheless, previous reports illustrate the importance of targeting SIRT1 in other cancer cells." (PMID 23460888, 2013). "For example, N-Myc and c-Myc complete positive feedback loops that promote SIRT1 expression and activity, and the negative regulator of SIRT1 hypermethylated in cancer 1 (HIC1) is commonly epigenetically repressed in cancer, allowing for an increase in SIRT1 activity." (PMID 24258275, 2013). "Since varied reports on tumor suppressor function of SIRT1 have been reported, SIRT1 activators could be useful for treatment or prevention of certain type of cancers." (PMID 23846322, 2013). "SIRT1 was mainly expressed in the cytoplasm of cancer tissues." (PMID 24223900, 2013). "Since AKIP1 localizes to the nucleus and has been shown to modulate transcription via NFκB and SIRT1 in cancer cell lines, the mitochondrial changes may be a result of altered transcription of nuclear encoded mitochondrial genes." (PMID 24236204, 2013). "The functional role of Sirt1 in cancer is equivocal and suggested to be context dependent." (PMID 24088390, 2013). "Moreover, SIRT1 inhibition has been reported to suppress cell growth and induce cell cycle arrest or apoptosis in cancer cells." (PMID 24137378, 2013). "However, consistent with its potential anti-oncogenic role, SIRT1 expression was found to be decreased in a subset of human cancers." (PMID 23799088, 2013). "The possibility that SIRT1 could be a therapeutic target of human cancer has also been suggested in xenograft tumorigenic assays." (PMID 24019980, 2013). "In addition, overexpression of SIRT1 induced chemoresistance of cancer cells by up-regulating P-glycoprotein expression." (PMID 24019980, 2013). "Collectively, these studies suggest that SIRT1 could serve as a novel potent pharmacological target of cancer chemotherapy." (PMID 24223900, 2013). "However, cellular and molecular studies have revealed a pleiotropic role for SIRT1 in cancer, as it acts as a tumour promoter post-cancer formation." (PMID 24258275, 2013). "However, ectopic expression of SIRT1 increases the proliferation of cancer cells and blocks stress-induced apoptosis." (PMID 24019980, 2013). "In contrast, SIRT1 inhibitor can induces senescence-like growth arrest with attenuated Ras-MAPK signaling in human cancer cells, suggesting that SIRT1 inhibitors may have anticancer potential." (PMID 24223900, 2013).
cancer (continued). "Meanwhile, the IC50 concentration of cisplatin for cancer cells decreased significantly from 6.34 ug/ml in control cells and 1.61 ug/ml in SIRT1 si-RNA-transfected cells, indicating that SIRT1 silencing significantly enhanced the chemosensitivity of H292 cells to cisplatin treatment." (PMID 24223900, 2013). "Additionally, in preclinical studies the phytochemical resveratrol activates SIRT1 and reduces cancer development in several models." (PMID 24280167, 2013). "Furthermore, inhibition of SIRT1 inhibited the proliferation of cancer cells and triggered cancer cell death." (PMID 24019980, 2013). "In addition, the expression of SIRT1 increased in human cancer tissue and during experimental carcinogenesis." (PMID 24019980, 2013). "The regulatory loop between SIRT1 and miRNA might provide new opportunities for therapeutic tissue-specific regulation and cancer inhibition." (PMID 23497588, 2013). "SIRT1 expression was significantly higher in poorly differentiated carcinomas." (PMID 24088390, 2013). "The role of SIRT1 in human carcinomas has been extensively studied." (PMID 24019980, 2013). "In light of the therapeutic potential of targeting Csn5/Skp2 in cancer treatment, the ability of CG-12 to downregulate the expression of Csn5 and Skp2 through Sirt1 induction provides a proof-of-concept that the Csn5/Skp2 signaling axis represents a “druggable” target for this novel ERMA." (PMID 23071779, 2012). "Our results suggest that blockade of SIRT1 activity or/and gene expression may provide novel opportunities for anti-cancer treatment." (PMID 23028940, 2012). "One recent report suggested SIRT1 as a possible prognostic indicator of HCC but other report could not find prognostic significance of SIRT1 despite higher expression of SIRT1 in cancer tissue compared to adjacent normal tissue." (PMID 23024800, 2012). "An undesirable effect of inhibiting SIRT1 activity could be obtained if, for example, NF-κB is constitutively activated in the targeted cancer cells." (PMID 22479397, 2012). "SIRT1 suppresses NF-κB signaling and release of this suppression could stimulate cancer cell proliferation, inhibit apoptosis and increase angiogenesis and metastasis." (PMID 22479397, 2012). "In particular, it is important to determine whether the SIRT1 NLS and/or NES contain point mutation(s) in human cancer tissues." (PMID 23050959, 2012). "The differential subcellular localization of SIRT1 may affect the substrate specificity in normal versus cancer cells." (PMID 23050959, 2012). "The discovery of a SirT1 function in suppressing developmental genes could be a further clue for the correct interpretation its role in cancer." (PMID 21307403, 2011). "Small molecule SIRT1 inhibitors have shown promising anti-cancer effects both in vitro and in vivo." (PMID 21698133, 2011). "The role of Sirt1 in cancer is still in controversy, it could act as both tumor suppressor or tumor promoter." (PMID 21549004, 2011). "Based on the elevated levels of Sirt1 in cancers, it was hypothesized that Sirt1 serves as a tumor promoter." (PMID 21549004, 2011). "There are currently controversies and debates regarding the role of SIRT1 in cancer." (PMID 21698133, 2011). "The application of SirT1 inhibitors centers mainly on cancer therapy." (PMID 21307403, 2011).
cancer (continued). "Although there is still a long path to walk before we reach full understanding of the complex and intriguing role of sirtuins, a small step has been made towards comprehension of SirT1 function in stem cells, with possible implications for the related fields of cancer and aging." (PMID 21307403, 2011). "While SIRT1 may function as a tumor suppressor bylimiting replicative senescence in primary cells, SIRT1 overexpression is seenin many cancers where it may promote cell survival." (PMID 20634564, 2010). "Reintroduction of miRNAs lost in cancers thatoverexpress SIRT1 may be of therapeutic value against cancers dependent on theoverexpression of SIRT1." (PMID 20634564, 2010). "Thecurrent study also provides insight into general regulation of SIRT1 andspecific roles it may have in tumorigenesis and cancer." (PMID 20157516, 2009). "Furthermore, SIRT1 inhibition sensitizes cancer cells to apoptosis while sparing normal cells, making HDAC III inhibitors promising anti-cancer drugs." (PMID 18369442, 2008). "Additionally, SIRT1 was found to maintain silencing of E-cadherin, a gene mediating cell–cell adhesion that is also inactivated epigenetically in many cancers." (PMID 16596166, 2006). "Inhibition of SIRT1 by multiple approaches leads to TSG re-expression and a block in tumor-causing networks of cell signaling that are activated by loss of the TSGs in a wide range of cancers." (PMID 16596166, 2006). "Given that SIRT1 post-translationally modifies numerous substrate proteins across diverse cellular pathways, precise control of its activity could serve as an effective therapeutic strategy in cancer treatment." (PMID 41304625, 2025). "Therefore, the selective targeting of SIRT1 in cancer cells through tumor-specific delivery systems, context-dependent inhibitors, or exploitation of cancer-specific redox vulnerabilities should be prioritized to maximize therapeutic benefits while minimizing harm to normal tissues." (PMID 41008982, 2025). "Consequently, novel derivatives endowed with higher SIRT1 selectivity, along with improved potency, might lead to more promising outcomes, especially in cancer." (PMID 39215785, 2025). "Integration of genomic data (e.g., SNPs in SIRT1, SIRT3, PGC‐1α), transcriptomic signatures (e.g., inflammatory and proliferative gene expression), and metabolomic profiles (e.g., NAD+/NADH ratio, redox metabolites) can identify individuals at high cancer risk." (PMID 40673471, 2025). "Combining SIRT1 inhibitors with existing cancer therapies, such as immune checkpoint inhibitors, may yield synergistic effects and provide personalized treatment options based on cancer-specific characteristics." (PMID 41008982, 2025). "SIRT1 may function also function as a tumor suppressor depending on the signaling pathways it targets, the significance of which may vary depending on the type of cancer." (PMID 41304967, 2025). "Sirt1 deacetylates both histone and non-histone proteins and is implicated in cancers." (PMID 40075208, 2025).
cancer (continued). "Moreover, SIRT1 is crucial in negatively regulating cancer cells' PI3K/AKT pathway." (PMID 40708783, 2025). "In addition, omega-3 fatty acids induce cancer cell apoptosis by accumulating reactive oxygen species (ROS) and activating caspases, and also activate autophagy flux through SIRT1-mediated Beclin-1 deacetylation and AMPK pathway, thereby alleviating oxidative stress and inflammation." (PMID 40761352, 2025). "However, clinical trials specifically targeting SIRT1 in these cancers remain limited." (PMID 41300302, 2025). "Nevertheless, whether arzanol’s SIRT1 inhibition contributes to its anticancer effects requires cancer cell-specific studies examining SIRT1 and FOXO1 expression and activity following arzanol treatment, complemented measuring SIRT1 overexpression or comparison with selective SIRT1 inhibitors." (PMID 41304625, 2025). "However, this requires further investigation, as SIRT1 may function as both oncogenes and tumor suppressors in cancers." (PMID 41170449, 2025). "Therefore, it is important to understand the comprehensive role of SIRT1 in cancer management." (PMID 38539819, 2024). "However, we observed significant differences in SIRT1 expression across different cancer types." (PMID 39845948, 2024). "Therefore, understanding the regulatory mechanism of SIRT1 in distinct contexts is highly important and could contribute to therapeutic interventions for cancer." (PMID 38443596, 2024). "The combination of chemotherapy with other SIRT1 inhibitors, such as suramins, JGB1741, tenovins, salermide, sirtinol, and other class III HDAC inhibitors, might enhance the efficacy of cancer treatments by regulating autophagy and inducing associated cell death." (PMID 39403142, 2024). "Additionally, SIRT1 plays a role in the occurrence of ferroptosis in cancer." (PMID 39479446, 2024). "Therefore, SIRT1 is a key player in maintaining chromosomal stability and cellular function and is a significant target for research on aging and related diseases, such as cancer, neurodegenerative diseases, and metabolic disorders." (PMID 39845948, 2024). "Importantly, increasing evidence suggests that SIRT1 is a major player in cancer drug resistance." (PMID 38598008, 2024). "Finally, we validated SIRT1 expression in cancer cell lines through qRT–PCR and WB experiments." (PMID 39845948, 2024). "Importantly, SIRT1 upregulation is positively correlated with both a reduction in apoptosis and resistance to chemotherapeutic drugs, including doxorubicin, in various types of cancer and in cancer stem cells." (PMID 38443596, 2024). "However, further studies might be required to expand the understanding of SIRT1 ISGylation in various cancers." (PMID 38443596, 2024). "It has been shown to have anti-inflammatory, antioxidant, and anti-cancer properties and may also promote longevity by activating certain enzymes and transcription factors (i.e., SIRT-1, and Nrf2) that are involved in the regulation of cellular and molecular processes of aging." (PMID 38012365, 2024). "SIRT1 and c-Myc may establish a positive feedback loop in cancer cells." (PMID 38397988, 2024). "Given the role of SIRT1 as a regulator of autophagy, further exploration into how SIRT1-mediated autophagy might influence ferroptosis is warranted, offering potential new avenues for cancer therapy." (PMID 39403142, 2024). "SIRT2 expression may vary significantly in various types of cancers, much like SIRT1." (PMID 37175631, 2023). "Many studies have demonstrated that SIRT1 was overexpressed in prostate, liver, lymphoma, colon, breast and gastric cancers; and it is thought that inhibiting its activity could be a potential strategy for cancer treatment." (PMID 37242510, 2023).
cancer (continued). "The modulation of SIRT1 activity could significantly impact the efficacy of cancer treatments." (PMID 38203666, 2023). "While the inclusion of estradiol replacement therapy appears to be a promising means of restoring SIRT1 expression and activity, at the same time, it also appears that estradiol shapes SIRT1 expression in cancer cells, which may lead to the unwanted progress of cancerogenesis and metastasis." (PMID 37762053, 2023). "Moreover, the reduction of SIRT1 in lovastatin/AC extract-treated PC3 cells might contribute to not only growth inhibition but also mitigated cancer stemness." (PMID 37960146, 2023). "In addition, Jiao, F. and Z. Gongamong also showed that seven sirtuins, SIRT1, play an significant regulatory role in a wide range of physiological processes, including oxidative stress, regulation of synaptic plasticity, metabolism as well as cancer." (PMID 37742223, 2023). "Cancer cachexia may be prevented and treated by targeting SIRT1." (PMID 37190306, 2023). "In addition, silent information regulator 1 (SIRT1) enhances tumorigenesis and metastasis via the deacetylation of tumor suppressors and also increases glucolipid metabolic conversion to facilitate cancer progression." (PMID 37762214, 2023). "Therefore, inactivating the positive feedback loop between KRASMut and SIRT1 by reducing the SIRT1 level could be an attractive therapeutic strategy for KRASMut cancer." (PMID 37779142, 2023). "We studied the effects of aging and SIRT1 activity on replication origin usage and the incidence of transcription–replication collisions (creating R-loop structures) in adult human cells obtained at different time points during chronological aging and in cancer cells." (PMID 37998365, 2023). "Moreover, using a phosphoproteomics approach, we previously assessed the enzymatic activity of three enzymes associated with cancer and only present in sEVs derived from the cancerous cell lines MCF7 and MDA-MB-231: ATP citrate lyase (ACLY), sirtuin-1 (SIRT1) and sirtuin-6 (SIRT6)." (PMID 37189694, 2023). "We used the SIRT1 inhibitor Ex-527 (0.1 μM, the tumor cell model was used to select the dose) to investigate whether SIRT1 activation mediated the therapeutic effect of UA on cancer cachexia and evaluated its effects on myotube atrophy in vitro." (PMID 37190306, 2023). "However, the effects of SIRT1 as a cancer promoter or a suppressor are still poorly understood." (PMID 37715252, 2023). "Next, we studied whether β-conglutins regulated stemness in our in vitro model of BC since SIRT1 was identified as a central regulator of progression and metastasis in BC through cancer stem cells (CSCs) and the therapeutic potential of this subpopulation was also described recently." (PMID 36771230, 2023). "Notably, whereas the level of SIRT1 protein variably increased or decreased from nontumor to tumor tissues in different patients, acetylation of its specific substrate H3K9 consistently increased in tumor samples, reflecting SIRT1 inactivation as found in carcinoma cell lines." (PMID 37530744, 2023). "Therefore, in the context of cancer, it can be hypothesized that SIRT1-NAT induction other than disruption might be the appropriate strategy to control the growth of cancer cells." (PMID 36138054, 2022). "Moreover, modulation of the SIRT1 enzyme seems to be responsible for the pharmacological effects of resveratrol in non-vascular cells, such as tenocytes, chondrocytes, fibroblasts, and cancer cells." (PMID 36499460, 2022).